IL22 (interleukin 22)
Diseases named in the same sentence as IL22 in open-access papers (continued):
Sharing a sentence is not in itself a finding about the gene and the disease.
asthma (continued). "Therefore, we hypothesized that DEP-PAH, and some purified PAH previously shown to be involved in asthma, might affect, through their effects on AhR, IL-17 and IL-22 cytokine profiles." (PMID 25860963, 2015). "However, no study has been performed to show the direct tissue effects of IL-22 in the lung and whether IL-22 expressed in the airways has regulatory effects on allergen induced asthma." (PMID 25254361, 2014). "A study included allergic asthma (n = 18), controlled asthma (n = 17) and healthy controls (n = 12) found that IL-22 might be involved in the pathogenesis of allergic asthma in human and the level of IL-22 might have some relationship with the severity of the disease (P< 0.05)." (PMID 25297677, 2014). "Considering the contribution of percutaneous priming for the development of atopic march, a progression from eczema to allergic rhinitis and asthma, their finding may suggest that IL-22 plays a role in percutaneous sensitization and thus the development of asthma in patients with eczema." (PMID 23577040, 2013). "In severe asthma, there is significantly higher expression of TGF-β1 compared to milder forms of asthma, suggesting the possibility that, in severe asthma, IL-22 may have different effects than in acute or mild disease because of the associated expression of TGF-β1." (PMID 24283210, 2013). "Th17 cells are distinct population of CD4+ T cells that produce IL-17A, IL-17F and IL-22 and are involved in the pathogenesis of a variety of inflammatory conditions including experimental autoimmune encephalomyelitis, collagen-induced arthritis, psoriasis, allergy and asthma." (PMID 24349168, 2013). "Taken together, these human studies suggest that IL-22 plays inhibitory roles in the development of allergic airway inflammation in asthma patients, but it could promote airway remodeling if its expression is uncontrolled during the resolution phase of allergic inflammation." (PMID 23577040, 2013). "Our findings indicate that several cytokines, including IL-5, IL-17A, IL-22, IL-33, TNF-α, leptin, and IL-10 were independently influenced by asthma and obesity." (PMID 39902293, 2024). "Given the preponderant role of IL-17 and IL-22 in neutrophil recruitment, this supports the involvement of both of these cytokines in EMT in asthma." (PMID 35386663, 2022). "Our findings provide strong evidence that the down-regulation of miRNA-221-5p increased IL-6, IL-17, IL-21 and IL-22 levels, and reduced IL-10, IL-35 and TGF-β levels in vitro model of asthma." (PMID 34863307, 2021). "On the one hand, the concentration of IL-22 significantly increases in peripheral blood mononuclear cells (PBMC), serum and lung tissues of asthma patients compared with healthy controls." (PMID 34836520, 2021). "IL-22 expression was reported to be increased in peripheral blood mononuclear cells (PBMC) from both children and adults with asthma." (PMID 28231834, 2017). "IL-23 and IL-1β rapidly stimulate ILC3s to produce IL-22, which plays a protective role through lung epithelial cells during TH2 asthma." (PMID 26150907, 2015). "We generated mice carrying transgenes CC10-rtTA or SPC-rtTA and TRE-Tight-IL-22 (CC10-rtTA-IL-22) or (SPC-rtTA-IL-22) and these mice were used in the OVA-induced asthma experiments." (PMID 25254361, 2014). "The majority of IL-22-producing cells in peripheral blood of asthma patients are CD4+CCR6+CD161+ cells, suggesting that Th17 cells are the main producer of IL-22." (PMID 23577040, 2013). "However, it fails to explain more severe forms of asthma that are often associated with the expression of Th1 cytokines such as interferon-γ and the more recently described Th17-associated cytokines IL-17 and IL-22." (PMID 24283210, 2013). "Thus, IL-22 signalling modulation may be useful for the treatment of asthma." (PMID 18315837, 2008). "Anti-IL-22 therapies have not been evaluated in asthma yet but were demonstrated efficient in severe atopic dermatitis including an effect on skin remodeling." (PMID 35386663, 2022).
asthma (continued). "Paradoxically, in another murine model of dog allergen-induced asthma, which reproduces the characteristics of airway remodeling, Aryl hydrocarbon receptor antagonism decreased IL-22 levels (but not IL-17) in lungs together with decreased airway remodeling." (PMID 35386663, 2022). "Although there are no currently clinical studies of IL-22 targeting therapies in asthma, some data suggest a potential role for such therapies." (PMID 35386663, 2022). "Nontype 2 endotype asthma, also called T2 low asthma, is characterized by neutrophilic or paucigranulocytic airway inflammation, driven by cytokines such as IL-8, IL-17 and IL-22." (PMID 34680614, 2021). "Therefore, we explored the effect of IL-22 on allergic airway inflammation and airway hyperresponsiveness (AHR) in an ovalbumin (OVA)-induced asthma mouse model." (PMID 34836520, 2021). "The inhibition of FOXP3 attenuated the effects of miRNA-221-5p on the inhibition of IL-6, IL-17, IL-21 and IL-22 levels, and promotion of IL-10, IL-35 and TGF-β levels in in vitro model of asthma following anti-miRNA-221-5p, in comparison with anti-miRNA-221-5p group." (PMID 34863307, 2021). "The inhibition of SOCS1 attenuated the effects of anti-miRNA-221-5p on the increased levels of IL-6, IL-17, IL-21 and IL-22, and suppressed levels of IL-10, IL-35 and TGF-β in in vitro model of asthma following anti-miRNA-221-5p, compared with anti-miRNA-221-5p group." (PMID 34863307, 2021). "The inhibition of RORγt also attenuated the effects of anti-miRNA-221-5p on the increased levels of IL-6, IL-17, IL-21 and IL-22 levels, and inhibited levels of IL-10, IL-35 and TGF-β in in vitro model of asthma following anti-miRNA-221-5p, in comparison with anti-miRNA-221-5p group." (PMID 34863307, 2021). "The therapeutic potential of IL-22 has been studied in a variety of disease processes including GVHD of the gut, colitis, inflammatory skin disorders, and inflammatory conditions of the lung such as asthma and fibrosis." (PMID 32637365, 2020). "It was found that IL-17A, IL-17F and IL-22 were increased in peripheral blood mononuclear cells (PBMCs), bronchoalveolar lavage fluid (BALF) and sputum of asthmatic patients, mainly in those with severe asthma." (PMID 33013382, 2020). "Th17 cells produce some pro-inflammatory cytokines, particularly IL-17A, IL-17F, IL-21, IL-22, TNF-α, and GM-CSF, which may have important roles in the reinforcement of severe form of asthma." (PMID 30116273, 2018). "VEGF was significantly increased in children with STRA compared with controls without asthma when IL-17A and IL-22 were used in combination (Fig E5, A; P = .04)." (PMID 27746241, 2017). "Interestingly, recent studies have shown that IL-22, one of Th17 cell-derived cytokines, is detected in bronchoalveolar lavage fluid (BALF) in murine asthma models." (PMID 23577040, 2013). "We have also shown that NK cells, DCs, and LTi-like cells do not express IL-22 mRNA in the lung in the murine asthma model." (PMID 23577040, 2013). "The distribution of the IL-22 receptor suggests that IL-22 signals predominantly in non-immune cells and therefore holds particular interest for certain features of asthma, including airway remodeling." (PMID 24283210, 2013). "Although we were previously able to demonstrate enhanced expression of sputum IL‐22 protein and the IL‐22/Fezakinumab gene response signature in patients with severe asthma, the numbers in OAC clusters 2 and 4 did not generate significant differences in this study." (PMID 39073027, 2024). "Moreover, during the comorbidity asthma and pneumonia that induces neutrophil inflammation, IL-22 was not detrimental." (PMID 37445595, 2023). "Although some studies suggest that IL-22 may exhibit inhibitory effects on airway inflammation in asthma by inhibiting the action of IFN-γ on epithelial cells, there are still few studies exploring the mechanisms of IL-22 and human asthma pathophysiology." (PMID 37377958, 2023).
asthma (continued). "Therefore, IL-17 and IL-22 are attractive therapeutic targets for new biotherapies in severe asthma while there is currently no pharmacological treatment targeting airway remodeling." (PMID 35386663, 2022). "While viral-induced dysregulation of ILC2 responses can lead to exacerbated asthma, ILC3-derived IL-22 can limit airway hyperreactivity, which suggests that ILC3 homeostasis may also be negatively impacted during respiratory infections in addition to mucosal infections." (PMID 30893756, 2019). "Importantly, anti-IL-22 antibody treatment significantly enhances the expression of IL-25, one of the epithelial cell-derived cytokines which promote Th2 responses, in the BALF in a murine model of asthma." (PMID 23577040, 2013). "IL-22 alone did not have a discernible effect on the morphology of cultured primary bronchial epithelial cells taken from normal subjects or those obtained from patients with mild and severe asthma." (PMID 24283210, 2013). "Our finding that IL-22 phosphorylates STAT3, a signal transducer of IL-22, in lung epithelial cell line further suggests that functional IL-22 receptor complex is expressed on lung epithelial cells and that direct targets of IL-22 in a murine model of asthma are lung epithelial cells." (PMID 23577040, 2013). "Furthermore, IL-22 has been shown to inhibit the expression of CCL17, which induces the recruitment of activated T cells into the lung, in a murine Clara cell line as well as in a murine model of asthma." (PMID 23577040, 2013). "However, the contribution neither of IL-22 nor of IL-26 to asthma pathogenesis has been understood so far." (PMID 20976014, 2010). "Consequently, IL-17, IL-22, and IL-6, rather than Th2 cytokines, may be clinically relevant in obese patients with severe asthma." (PMID 36078171, 2022). "The expression of miRNA-221-5p was increased in model of asthma, compared with negative group The vitro model of asthma treated with miRNA-221-5p mimic resulted in the reduction of IL-6, IL-17, IL-21 and IL-22 levels, and induction of IL-10, IL-35 and TGF-β levels." (PMID 34863307, 2021). "Down-regulation of miRNA-221-5p increased the levels of IL-6, IL-17, IL-21 and IL-22, and reduced those of IL-10, IL-35 and TGF-β in in vitro model of asthma, compared with negative group." (PMID 34863307, 2021). "Because IL-17A is associated with increased numbers of neutrophils in adults with asthma, levels of GRO were measured in BAL fluid as well as in PBEC culture supernatants following IL-17A and IL-22 stimulation, with or without budesonide." (PMID 27746241, 2017). "It is of note that although the chosen PAH have been shown to enhance allergen-induced experimental asthma, only DEP-PAH and BaP modulated IL-17A and IL-22 production, showing that not all AhR ligands behave similarly." (PMID 25860963, 2015). "Neutrophilic inflammation, CXCL-1 levels and pulmonary inflammation were not significantly different when comparing WT OVA+Sp and IL-22 KO OVA+Sp groups, suggesting that IL-22 is not involved in the comorbidity asthma and acute pneumonia that courses with neutrophilic inflammation." (PMID 37445595, 2023). "We tested this hypothesis by comparing plasma cytokines, including IL-2, IL-5, IL-10, IL-13, IL-17A, IL-22, IL-33, IFN-γ, and TNF-α and the adipokine, leptin in normal weight and overweight/obese children, both with and without asthma in a cross-sectional study." (PMID 39902293, 2024).
rheumatoid arthritis (88 papers, 2010 to 2026). A chronic, systemic autoimmune disorder characterized by inflammation in the synovial membranes and articular surfaces. "Elevated levels of IL22 secreted from T lymphocytes were implicated in rheumatoid arthritis and interstitial lung diseases." (PMID 37189778, 2023). "More recently, IL-22 serum levels were demonstrated to be associated with radiographic progression in rheumatoid arthritis, which further improved the importance of IL-22 in chronic inflammatory arthritis." (PMID 22485125, 2012). "The parasitic worm ES product has a protective effect against disease in a mouse collagen-induced arthritis model of rheumatoid arthritis (RA) by suppressing pathogenic IL-17 and upregulating IL-22 production by recruiting γδ T cells." (PMID 29163443, 2017). "Pathogenic Th17 cell, as a special Th17 cell subset, triggered and aggravated the immune response of chronic inflammatory diseases, such as periodontitis, IBD, and rheumatoid arthritis, through IL-17, IL-21, IL-22, IL-23, and GM-CSF (gene: CSF2)." (PMID 41318555, 2025). "IL-22 in pathological conditions such as rheumatoid arthritis by upregulating RANKL expression and IL-15 synergistically enhancing RANKL induced osteoclast differentiation." (PMID 36151243, 2022). "A range of studies have shown that patients with rheumatoid arthritis and psoriatic arthritis frequently have abnormal IL-22 expression." (PMID 34917427, 2021). "The drug significantly regulates the cytokines IFN-γ, IL6, IL17F, and IL22 s in peripheral blood mononuclear cells of rheumatoid arthritis subjects." (PMID 34064039, 2021). "Interestingly, the IL-22 system has also been linked to a range of T cell driven inflammatory diseases such as rheumatoid arthritis (RA), graft versus host disease (GvHD), and multiple sclerosis (MS)." (PMID 33692792, 2021). "IL-22 levels are elevated in patients with rheumatoid arthritis and there is a relationship between its level and radiographic progression and disease activity." (PMID 33515210, 2021). "IL-22 promoted inflammatory response and osteoclast formation in rheumatoid arthritis via the promotion of fibroblast-like synoviocytes proliferation and monocyte chemoattractant protein (MCP) expression." (PMID 34917427, 2021). "An analysis of inflammation in rheumatoid arthritis also showed the beneficial effect of vitamin D in reducing the concentration of IL-22 produced by activated memory T cells." (PMID 33435598, 2021). "The elevated serum level of IL-22 protein or mRNA transcripts were shown in Crohn’s disease, interstitial lung diseases, and rheumatoid arthritis that are correlated with disease severity." (PMID 35154603, 2021). "It has been reported that serum levels of IL-25 are significantly correlated with IL-22 in rheumatoid arthritis patients." (PMID 34388961, 2021). "The interaction between IL-22R1 and IL-22 is thought to contribute to synovial inflammation in rheumatoid arthritis." (PMID 30159338, 2018). "Recent studies show that IL-22 induces the proliferation of human epidermal keratinocytes obtained from healthy individuals and synoviocytes isolated from psoriatic arthritis, rheumatoid arthritis, and osteoarthritis patients." (PMID 28558005, 2017). "This type of non-traditional expression of IL-22 can be found in patients with diseases outside the GI tract such as rheumatoid arthritis (RA), where fibroblasts have been found to contribute to the production of IL-22." (PMID 26793707, 2015). "Increased plasma IL-22 level was found in patients with psoriasis, rheumatoid arthritis and Crohn disease." (PMID 24312440, 2013). "Both IL-17A and IL-22 have been shown to be pro-inflammatory cytokines that participate in the pathogenesis of autoimmune diseases, such as rheumatoid arthritis (RA), Crohn’s disease, systemic lupus erythematosus (SLE), and psoriasis." (PMID 23874630, 2013).
rheumatoid arthritis (continued). "Flow cytometry was used to enumerate cells making IL-22 and IL-17, in skin and/or SF and PB from 11 patients with Ps and 12 patients with PsA; skin and PB of 15 healthy controls and SF from rheumatoid arthritis (RA) patients were used as controls." (PMID 24286492, 2013). "The roles of both Th22 cells and IL-22 in the pathogenesis of ankylosing spondylitis and rheumatoid arthritis are still unclear and remain to be clarified." (PMID 22485125, 2012). "IL-22 is highly expressed in rheumatoid arthritis (RA), in which IL-22 induces production of monocyte chemoattractant protein-1 (CCL2; also known as MCP-1) and proliferation of synovial fibroblasts and osteoclasts." (PMID 22312190, 2012). "In this review, we will discuss the role of IL-22 in several CTDs, such as system lupus erythematosus, rheumatoid arthritis, Sjögren’s syndrome, systemic sclerosis and dermatomyositis, suggesting that IL-22 may be a potential therapeutic target in CTDs." (PMID 33407883, 2021). "Recently, IL-22 SNPs are reported to be involved in systemic sclerosis and rheumatoid arthritis." (PMID 30984790, 2019). "The objective of the present study was to evaluate the effects of Enalapril, Losartan and Valsartan on the production of IL-2, IL-10, IL-6, TNF, IFN-γ, IL-17A, IL-17F and IL-22 cytokines in PBMCs of patients with rheumatoid arthritis and evaluate this modulation with disease activity." (PMID 30288187, 2018). "A top pathway in both breeds is Role of Macrophages, Fibroblasts and Endothelial Cells in Rheumatoid Arthritis, which is a disease characterized by uncontrolled inflammation, and we observed upregulation of genes such as IL-1beta, IL-6, and IL-22 which are pro-inflammatory cytokines." (PMID 28166270, 2017). "IL-22 induces the proliferation of normal human epidermal keratinocytes obtained from healthy individuals and fibroblasts like synoviocytes isolated from psoriatic arthritis, rheumatoid arthritis and osteoarthritis patients." (PMID 27166675, 2016). "IL-22 is involved in airway inflammation, as well as protection from liver inflammation, activation of fibroblasts, and wound repair; IL-22 is also involved in rheumatoid arthritis and systemic sclerosis." (PMID 26583093, 2015). "In this study, we characterized cells making IL-22 and/or IL-17 in skin, synovial fluid (SF), synovial tissue (ST) and peripheral blood (PB) of Ps and PsA patients, together with PB and skin from healthy controls and SF from rheumatoid arthritis (RA) patients." (PMID 24286492, 2013). "For example, it is tempting to speculate that therapeutic efficacy of IL-1Ra in some rheumatoid arthritis patients may in part be mediated by ill-fated IL-1-induced IL-22 in these individuals." (PMID 20976193, 2010). "Overproduced cytokines of Th17 cells, especially IL-17A, IL-17F, IL-21, and IL-22, play a role in osteodestructive diseases such as rheumatoid arthritis (RA) and PD." (PMID 36983201, 2023). "Besides, Th22 cells and IL-22 level were significantly elevated in patients with rheumatoid arthritis (RA) and ankylosing spondylitis (AS) when compared with healthy controls, indicating that Th22 cells may be implicated in the pathogenesis of AS and RA." (PMID 31501353, 2019). "It seems that IL-22 is closely related with autoimmune diseases such as rheumatoid arthritis (RA), Crohn’s disease, and skin inflammatory diseases by promoting inflammatory responses." (PMID 27166675, 2016). "In autoantibody-driven rheumatoid arthritis, TH17 cells regulated the expression of β-galactoside α2,6-sialyltransferase 1 through IL-22 and IL-21, which induced glycan changes in autoantibodies coinciding with the inflammatory phase of arthritis." (PMID 39680460, 2024). "In vitro experiments have shown that the JBQG drug serum can inhibit the expression of cytokines (IL-6, IL-8, IL-22, IL-23), chemokine proteins and mRNA expression (MMP-1, MMP-2, MMP-3, MMP-9, MMP-13) in rheumatoid arthritis synovial fibroblasts (RA-FLS)." (PMID 37180723, 2023).